IRS1 (insulin receptor substrate 1)
Diseases named in the same sentence as IRS1 in open-access papers (continued):
Sharing a sentence is not in itself a finding about the gene and the disease.
Insulin resistance (continued). "Importantly, chronic APN deficiency due to AMPK inactivation causes cerebral insulin resistance in mice, i.e., increases IRS-1 phosphorylation at serine 616 and inhibits the formation of pIRS-1Tyr in neurons, leading AD-like pathologies." (PMID 31963819, 2020). "The present study provides evidence supporting the idea that hyperinsulinemic condition causes neuronal insulin resistance as indicated by the decreased phosphorylation of insulin receptors and their downstream signaling molecules, including IRS-1, AKT/PKB, and GSK-3β." (PMID 32138327, 2020). "BCAA overload may cause insulin resistance by the activation of mTOR signaling, resulting in persistent IRS-1 phosphorylation by mTORC1 and inhibition of insulin signaling." (PMID 32178221, 2020). "Similarly, p70 S6K, the downstream effector of mTOR, is implicated in the serine phosphorylation of IRS-1, leading to impaired insulin signaling and insulin resistance." (PMID 32664532, 2020). "Additionally, p70 S6K, the downstream effector of mTOR, has been shown to cause serine phosphorylation of IRS-1, resulting in impaired insulin signaling and insulin resistance." (PMID 32230718, 2020). "In this study, we hypothesized that FFA would increase serine phosphorylation of IRS1 in cultured podocytes and the kidney of a type 2 diabetic mouse model causing insulin resistance and renal dysfunction." (PMID 33303821, 2020). "The results of the current study are similar to those of a review paper showing that the loss of IRS-1 is indicative of insulin resistance, and this loss is correlated to the inactivation of hepatic PI3K and Akt resulting in diabetes (hyperglycemia and hyperinsulinemia) and hypolipidemia." (PMID 31171927, 2019). "A possible mechanism by which amino acids, and especially BCAAs, are implicated in insulin resistance (IR) might be the upregulation of mTORC1 through the phosphorylation of insulin receptor substrate 1 (IRS-1)." (PMID 30909557, 2019). "Human and animal model studies revealed that AD is associated with reduced insulin levels in the CSF and with insulin resistance, as well as with lower levels of the insulin receptor substrate IRS1 and higher levels of p-IRS1, which is a marker of brain insulin resistance." (PMID 30890171, 2019). "The degradation of IRS-1 is one of the primary mechanisms that could cause insulin resistance when exposed to pro-inflammatory cytokines." (PMID 31656196, 2019). "Our results demonstrating increased IRS1/O-GlcNAc association in adipose tissue suggest that O-linked GlcNAc post-translational modification may induce insulin resistance in this tissue." (PMID 30832230, 2019). "Moreover, the consumption of chokeberry and dried jujube changed the hepatic protein expression of insulin receptor, insulin receptor substrate 1, phosphoinositide 3-kinase, Akt, and catalase, which are associated with insulin resistance." (PMID 31171927, 2019). "Of the top 19 SNPs shared between T2D and CAD, the insulin receptor substrate 1 (IRS1) region (2q36.3) is one of the most interesting, with the four shared top SNPs being associated with T2D, insulin resistance, hyperinsulinemia, tryglicerides, and HDL cholesterol levels." (PMID 29309429, 2018). "Recent studies have revealed that ER stress-mediated activation of JNK has been associated with insulin resistance through phosphorylation of insulin receptor substrate-1 (IRS1) on Ser307, which leads to the reduction of tyrosine phosphorylation and IRS1 activation." (PMID 30425746, 2018). "In T2DM, the c-Jun N-terminal kinase (JNK) pathway is stimulated by the TNF-α cascade, thereby initiating peripheral insulin resistance, causing IRS-1 inhibition at the brain level and the interruption of downstream cascade favoring tau hyperphosphorylation and amyloid assembly." (PMID 30154946, 2018).
Insulin resistance (continued). "The protein c-Jun N-terminal kinase (JNK) has been increasingly recognized as an important mediator of insulin resistance that is associated with inflammation and oxidative stress through the phosphorylation of serine residues in insulin receptor substrate-1 (IRS-1)." (PMID 29433422, 2018). "The mechanism by which IKKβ causes insulin resistance is that it could directly enhance IRS-1 phosphorylation on Ser307, a key inhibitory site of IRS/PI3K/Akt pathway." (PMID 29473848, 2018). "These analyses revealed that selective insulin resistance occurs in the human liver, and that differential expression patterns of IRS-1 and IRS-2 may contribute to the underlying mechanism." (PMID 29717275, 2018). "Down-regulation of phosphorylated IRS-1 or Akt proteins, has been shown to inactivate downstream signaling events and subsequently reduce glucose uptake and cause hyperglycemia and peripheral insulin resistance." (PMID 29121676, 2017). "IRS1 mutations are associated to insulin resistance and type II diabetes." (PMID 29292732, 2017). "Therefore, inhibition of C1-Ten-mediated IRS-1 degradation suggests a novel therapeutic strategy for insulin-resistance-associated metabolic syndrome via dual targeting of IRS-1/Akt and IRS-1/AMPK." (PMID 29259227, 2017). "It has long been known that the insulin resistance in type 2 diabetes is caused by decrease in receptor concentration and kinase activity, the concentration and phosphorylation of insulin receptor substrate-1/−2, PI3K activity, and glucose transporter translocation." (PMID 29164077, 2017). "For example, decreased expression of insulin receptor substrate-1 (IRS-1) or reduced serine phosphorylation of this protein is associated with insulin resistance, and, importantly, such alterations influence downstream signaling via phosphatidylinositol-3 kinase (PI3K)." (PMID 27738449, 2016). "Hepatic insulin resistance is also associated with reduced expression of IRS-1 and IRS-2." (PMID 26866272, 2016). "This compound also has a positive effect on the endothelial dysfunction associated with insulin resistance by means of an IKKβ/IRS-1-dependent manner and therefore can be useful in the prevention or treatment of cardiovascular disorders involved in insulin resistance and diabetes." (PMID 28116217, 2016). "The phosphorylation of serine residues in insulin receptor substrate-1 leads to an impairment in the ability of IRS-1 to activate downstream phosphatidylinositol 3-kinase-dependent pathways which may cause insulin resistance." (PMID 27069930, 2016). "A prolonged oxidative stress and increased angiotensin II may cause insulin resistance thorough ROS-mediated activation of insulin receptor substrate-1 (IRS-1) of VSMCs." (PMID 26473856, 2015). "Thus, upon ET-1 activation, GRK2 associates with IRS-1 and promotes ET-1 mediated IRS-1 Ser612 phosphorylation and degradation which is associated with insulin resistance." (PMID 26474286, 2015). "Hyperinsulinemia and insulin resistance, which characterize diabetes, and the consequent upregulation of the insulin-like growth factor-1/insulin receptor substrate-1 system, may also explain the association between diabetes and HCC." (PMID 26074956, 2015). "In summary, we herein demonstrated for the first time the beneficial effects of L-Cit on improved insulin resistance associated with enhanced insulin sensitivity through the activation of IRS1 followed by the inhibition of serine 1101 phosphorylation both in vivo and in vitro." (PMID 26084330, 2015). "Excess fasting phosphorylation of muscle IRS‐1 at Ser636 may be a major cause of the insulin resistance seen in obesity and might prevent improvement in insulin responsiveness when exercise training is not accompanied by weight loss." (PMID 25472611, 2014). "Moreover, without affecting insulin receptor-mediated signal transduction, TNF-α can induce insulin resistance in adipocytes, characterized by loss of insulin receptor substrate-1 and GLUT4 expression." (PMID 24465695, 2014).
Insulin resistance (continued). "The pro-inflammatory cytokines TNFα and IL-6 have been shown to trigger phosphorylation of IRS-1, thus exerting an inhibitory action on insulin signaling; accordingly, genetic ablation either of TNFα or of its receptor can improve insulin resistance caused by obesity in rodent models." (PMID 23698776, 2013). "The aim of our present study is to determine the effect of Gelam honey extract and quercetin on the stress activated NF-κB and MAPK pathways and IRS-1 serine phosphorylation causing insulin resistance and the Akt activated insulin signaling pathway, causing increase in insulin content." (PMID 24324490, 2013). "The present findings demonstrate that tectorigenin attenuated insulin resistance (IR) associated with endothelial dysfunction through inhibiting ROS-related inflammation in endothelium cells, as well as facilitating insulin IRS-1/PI3K/Akt/eNOS signaling pathway." (PMID 23840461, 2013). "Over expression of TNF causes insulin resistance through the inhibition of PI3K-mediated activation of insulin receptor substrate 1 (IRS-1) and insulin receptor substrate 2 (IRS-2), and tyrosine phosphorylation of the mitogen-activated protein kinases p42MAPK and p44MAPK." (PMID 22451839, 2012). "Previous research demonstrated that the proinflammatory cytokine TNFα blunts the insulin signaling pathway therefore causing insulin resistance by activating the JNK1/2 signaling pathway which is involved in serine phosphorylation of IRS1 (insulin receptor substrate 1)." (PMID 22506114, 2012). "Studies have also reported decreased IRS-1 expression in the skeletal muscle of patients with diabetes, and concluded that this could represent a marker for the risk of insulin resistance." (PMID 21464990, 2011). "Increased O-GlcNAcylation has been implicated in the development of insulin resistance increasing adipocyte lipid metabolism by direct modification of IRS1 and AMPK respectively; however, such results have been under conditions of sustained increases in HBP flux and O-GlcNAcylation." (PMID 21494549, 2011). "Using overexpression of miR-126, we determined whether IRS-1-targeting miRNA causes insulin resistance in hepatocytes." (PMID 21464990, 2011). "Therefore, it is likely that an increase in IRS-1 serine phosphorylation is associated with the development of insulin resistance induced by JNK overexpression." (PMID 20182627, 2010). "Given the critical role of insulin resistance in these patients it was informative in that molecules immediately down stream of the insulin receptor appeared to be down regulated, such as IRS1, CD36 and JAK1/2 (a tyrosine kinase associated with cytokine and metabolic signalling)." (PMID 18997871, 2008). "It would appear that there may be a racial difference in the mutated sites of IRS-1 polymorphisms featuring the similar insulin resistance." (PMID 16603055, 2006). "Thus, the phosphorylation of these serine residues in IRS-1 causes insulin resistance." (PMID 36836727, 2023). "The decreased expression of irs1 may cause insulin resistance." (PMID 38322156, 2023). "Prior work has demonstrated that decreased IRS1 expression, the gene encoding the insulin receptor substrate, causes insulin resistance—our work further suggests that impaired expansion of the gluteofemoral and abdominal subcutaneous fat depots may be involved in this physiological insult." (PMID 35773277, 2022). "Our data reveal that LLPS-derived IRS1 condensates may function as intracellular signal hubs to execute insulin signal transduction and that impaired formation of IRS1 condensates is associated with insulin resistance." (PMID 35790738, 2022). "Interestingly, one such genetic variant (the C allele of rs2943641) present in close proximity to IRS1 is associated with hyperinsulinemia and insulin resistance by negatively impacting the basal IRS1 levels and impairing insulin signaling in human skeletal muscle biopsy samples." (PMID 35842608, 2022).
Insulin resistance (continued). "Increased ROS levels may cause insulin resistance by triggering redox-sensitive pro-inflammatory cascades such as nuclear factor kappa B (NF-κB) and by altering the phosphorylation of the insulin receptor substrate 1 (IRS-1)." (PMID 34679738, 2021). "Thus, this genetic variant near IRS1 may increase the risk of postpartum diabetes in women with previous GDM through increased insulin resistance." (PMID 34801028, 2021). "Putting together these data leads to the hypothesis that a single molecular impairment in the pathway of insulin signaling, including an incomplete interaction between PIK3CA(OMIM association number, 171834) and IRS1, may lead to insulin resistance, as well as insulin secretion defect." (PMID 30884193, 2019). "Thus, insulin deficiency such as in STZ diabetic rats or deficient IRS1/PI3K/Akt signaling as occurs in insulin resistance, may affect adenosine handling by downregulating nucleosides uptake leading to chronically increased levels of adenosine." (PMID 28842605, 2017). "Furthermore, we investigated the effect of Gelam honey extract and quercetin on the stress activated NF-κB and MAPK pathways and IRS-1 serine phosphorylation causing insulin resistance and the Akt activated insulin signaling pathway, causing increase in insulin content." (PMID 27034691, 2016). "As INSR and IRS-1 expression is suppressed at the post-transcriptional level by miR-96 in hepatocytes, this study further examined whether the upregulation of miR-96 causes insulin resistance in hepatocytes." (PMID 28036389, 2016). "Therefore, the aim of our present study is to determine the effect of Gelam honey extract and quercetin on the JNK and IKK-β inflammatory pathways and IRS-1 serine phosphorylation which causes insulin resistance and the Akt activated insulin signaling pathway, which improves insulin resistance." (PMID 27034691, 2016). "Therefore in our present study, we determined the effect of Gelam honey extract and quercetin on the stress-activated NF-κB, MAPK pathways and IRS-1 serine phosphorylation causing insulin resistance and the Akt-activated insulin signaling pathway, causing increase in insulin content." (PMID 24324490, 2013). "Supporting this hypothesis, a genetic variant near IRS1, that is associated with reduced basal levels of IRS1 protein and decreased insulin induction of IRS1-associated PI-3K activity in human skeletal muscle biopsies, is associated with type 2 diabetes, insulin resistance and hyperinsulinemia." (PMID 23468892, 2013). "Interestingly, the variant rs2943650 (r2 = 1.00 with rs2943641) near IRS1 has been reported in a recent GWAS for percentage body fat with the fat percentage–decreasing allele being associated with (counterintuitively) higher levels of insulin resistance." (PMID 24392269, 2012). "While tyrosine phosphorylation of IRS-1 promotes insulin action, serine phosphorylation can inhibit insulin signaling, thereby contributing to the development of insulin resistance." (PMID 41599356, 2026). "Liraglutide treatment has been shown to ameliorate insulin resistance aberrations and decrease IRS-1 pS616 upregulation in mouse models of Alzheimer’s disease." (PMID 41326666, 2026). "In summary, sinapine was confirmed to improve insulin resistance by upregulating the mRNA expression of IRS1, PI3K, AKT, GSK3β and GS and interacting with the target proteins to affect their phosphorylation." (PMID 41497732, 2026). "Various differentially phosphorylated forms of IRS-1 have been considered pathological markers of insulin resistance in Alzheimer’s disease." (PMID 41326666, 2026). "A high‐protein diet worsens insulin resistance and β‐cell dysfunction in both normal and T2D mice by increasing hepatic inflammation and suppressing IRS‐1 signalling." (PMID 41388732, 2026). "Subsequent work showed that in palmitate- or HFD-induced models, Saa1 upregulation inhibited IRS-1 signaling via NF-κB activation, contributing to insulin resistance." (PMID 41313351, 2026).
Insulin resistance (continued). "Insulin resistance frequently arises from modifications and functional abnormalities in insulin receptors and downstream signalling molecules such as IRS‐1." (PMID 41388732, 2026). "Activation of JNK promotes the serine phosphorylation of insulin receptor substrate 1 (IRS-1), which disrupts the insulin receptor signaling pathway to influence glucose uptake, eventually resulting in insulin resistance." (PMID 40863244, 2025). "This inhibits Rhbdf2-TAK1 signaling and downstream JNK/NF-κB phosphorylation, and thus exerting a protective effect against NAFLD, including attenuating IRS1 phosphorylation-mediated insulin resistance and thereby inhibiting glucose production." (PMID 40292292, 2025). "Conversely, in insulin resistance, serine phosphorylation of IRS1 intensifies, impeding downstream signaling activation." (PMID 40565724, 2025). "SIL modulates metabolic reprogramming by reducing triglyceride accumulation in the liver, ameliorates insulin resistance through the IRS-1/PI3K/Akt pathways, and provides cardioprotection by attenuating injury markers while inhibiting apoptotic signaling." (PMID 40944191, 2025). "In mHypoE-46 neurons, treatment with 10nM insulin for 6 hours, which is prior to the development of cellular insulin resistance, still resulted in significant downregulation of Igf1r, Irs1, and Irs2." (PMID 40105689, 2025). "It is widely accepted that ROS can enhance the impairment of the IRS-1/PKB/GSK3β signaling and promote the phosphorylation of IRS at Ser residue, which is associated with insulin resistance." (PMID 40806739, 2025). "The crosstalk between NF-κB and c-Jun N-terminal kinase (JNK) pathways further amplifies insulin resistance, particularly through phosphorylation of insulin receptor substrate-1 (IRS-1), thereby impairing insulin signal transduction." (PMID 40868165, 2025). "The HFD induces brain insulin resistance by reducing the tyrosine phosphorylation of the insulin receptor and increasing the serine phosphorylation of insulin receptor substrate 1, which can disrupt the proteins involved in the insulin signaling pathway." (PMID 40149843, 2025). "Restores insulin sensitivity, enhances glucose uptake, reverses palmitate-induced insulin resistance, reduces IRS-1 serine phosphorylation, activates AMPK, improves GLUT4 translocation." (PMID 39963239, 2025). "The application of sacubitril+valsartan provided an important treatment for insulin resistance due to PCOS by increasing the expression of insulin resistance (IR), insulin receptor substrate 1 (IRS-1), and insulin receptor substrate 2 (IRS-2)." (PMID 41586197, 2025). "High sUA levels impair insulin signaling through inhibition of intrahepatic IRS1 and Akt pathways, thereby inducing insulin resistance." (PMID 40089555, 2025). "The findings demonstrated that JWQZG effectively reduces hepatic lipid accumulation and inflammation while improving insulin resistance through activation of the IRS1/PI3K/AKT/GSK3β pathway." (PMID 40221773, 2025). "The GLP-1RAs studied alleviated central insulin resistance, as evidenced by the decreased serine phosphorylation of insulin receptor substrate 1 (IRS-1) and restored downstream phosphoinositide 3-kinase/RAC serine/threonine–protein kinase (PI3K/Akt) signaling." (PMID 40430434, 2025). "This overactivated GSK3β can then phosphorylate insulin receptor substrate 1 (IRS1) at the Ser332 site, impairing insulin signaling and contributing to insulin resistance, a condition often associated with diabetic nephropathy." (PMID 40526103, 2025). "Reduced levels of Irs1 in adipocytes have been identified as a predictor of insulin resistance in human studies." (PMID 40822955, 2025). "Substantial S-nitrosylation of IR, IRS-1, and Akt has been observed in obese rodent models, inhibiting insulin signaling and promoting insulin resistance." (PMID 41226411, 2025).